IGF1R (insulin like growth factor 1 receptor)
Diseases named in the same sentence as IGF1R in open-access papers (continued):
Sharing a sentence is not in itself a finding about the gene and the disease.
breast cancer (continued). "There is evidence that PARP1 regulates estrogen-dependent breast cancer cell growth through the modulation of the estrogen receptor (ER)-insulin-like growth factor 1 receptor (IGF-1R)-Na(+)/H(+) exchange regulatory cofactor NHE-RF3 (PDZK1) axis." (PMID 30890936, 2019). "The current results demonstrate that both INSR and IGF1R exhibit a nuclear localization in breast cancer-derived cells." (PMID 31771180, 2019). "We demonstrate that both INSR and IGF1R exhibit a nuclear localization in breast cancer-derived cells." (PMID 31771180, 2019). "We found that HER2 interacted with both HER3 and IGF-1R, forming a heterotrimeric complex in trastuzumab-resistant breast cancer cells." (PMID 30930695, 2019). "IGF-1R has also been shown to be upregulated in tamoxifen-resistant breast cancer cells and to participate in antiestrogen resistance." (PMID 30692633, 2019). "Previous studies have shown that activation of the IGF-1R signaling pathway promotes proliferation, survival, and metastasis of breast cancer cells." (PMID 30692633, 2019). "There is a relationship between IGF-1R and survival in breast cancer and solid tumors, but IGF-1R expression in gastric cancer is poorly understood." (PMID 31318186, 2019). "IGF-1R up-regulates MUC1 expression in breast cancer cells in a PI3K/Akt signaling pathway-dependent manner and subsequently promotes epithelial-mesenchymal transition that is important in metastasis." (PMID 30041514, 2019). "Up‐regulation of miR‐122 suppressed cell growth and cell‐cycle progression in breast cancer cell lines and suppressed tumorigenesis in vivo by targeting IGF1R and regulating the PI3K/Akt/mTOR/p70S6K pathway." (PMID 30938061, 2019). "A randomized phase II trial of ridaforolimus with the IGF1R inhibitor dalotuzumab and exemestane (R/D/E) was compared with R/E in patients with advanced breast cancer." (PMID 31817676, 2019). "Expression of t-DARPP has been shown to activate IGF-1R signalling in trastuzumab resistant breast cancer cells through increased glycolytic capacity." (PMID 31740718, 2019). "More over downregulation of IR inhibits cancer metastasis in an athymic mouse breast cancer model, even in the presence of functional IGF1R, but these cells represent different metabolic abnormalities and FBP mediated metabolism deregulation." (PMID 30929166, 2019). "For example, probes targeting other RTKs besides HER2—such as HER3, VEGFR, and IGF-1R have been evaluated in breast cancer animal models." (PMID 31652624, 2019). "Prolonged treatment of breast cancer with IGF1R TKIs has also been observed to promote resistance via activation of an alternate RTK, TYRO3." (PMID 30653502, 2019). "Formononetin has also been shown to inhibit the upstream signals of the PI3K–AKT pathway by downregulating the expression of the insulin-like growth factor receptor (IGF-1R) in human breast cancer cells." (PMID 31402861, 2019). "The availability of MCF7 breast cancer cells with specific abrogation of the INSR or IGF1R allowed us to examine the effects of these pathways on the subcellular distribution and activation of the receptors as well as the downstream effectors." (PMID 31771180, 2019). "Examples include IGF1R gene amplification and mutation in other IGF axis genes, detected in breast cancer, gastrointestinal stromal tumor (GIST) and osteosarcoma." (PMID 31416218, 2019). "We detected interactions in the cytoplasm of a patient-derived breast xenograft (PDX) of ERα+ breast cancer that strongly expressed IGF-1R at the plasma membrane and in the cytoplasm, and quantified these." (PMID 30692633, 2019). "IGF-1R expression has different prognostic values for patients with breast cancers of different molecular subtypes." (PMID 30692633, 2019). "Subsequent to the reduction in IGF-1R expression levels resulted in reduce expressions of ER-α and PDZK1, associated with decreased risk of developing breast cancer metastasis." (PMID 29787591, 2018).
breast cancer (continued). "We assessed IGF1R and E‐cadherin expression in circulating tumor cells (CTCs) in patients with breast cancer." (PMID 28766847, 2018). "In another series, higher IGF1R mRNA expression levels in early breast cancer were correlated with favorable clinicopathological parameters and patient prognosis." (PMID 28766847, 2018). "The hybrid PN analysis obtained in this study resulted to identify the increased expression of IGF-1R, IRS-1 and ER-α drastically involved in increased risk of breast cancer metastasis." (PMID 29787591, 2018). "The insulin receptor (INSR) and the insulin growth factor 1 receptor (IGF1R) play important roles in the etiology of both diabetes mellitus and breast cancer." (PMID 29486734, 2018). "The direct molecular interaction between IGF-1R and PDZK1 enhances expression of ER-α associated with breast cancer metastasis." (PMID 29787591, 2018). "TGF-β-elicited EMT program augments expression of RTKs such as EGFR and IGF-1R which form cytoplasmic complexes with ER-α and Src leading to anti-estrogen resistance in breast cancer." (PMID 29455658, 2018). "Accordingly, despite the loss of highly glycosylated proIGF-1Ea after the 2-DG treatment, the condition media of these cells fully activated the IGF-1R of human breast cancer cell line MCF-7." (PMID 29891966, 2018). "IGF1R(+) CTCs are commonly detected in breast cancer, and their frequency decreases in the metastatic disease stage." (PMID 28766847, 2018). "Further analysis of the METABRIC dataset revealed an increase in IL-6, CCL2, and MMP-9 expression in patients with low IGF-1R, consistent with our mouse tumor model and data in human breast cancer cell lines." (PMID 30458886, 2018). "Combination of anti-HER2 drugs with anti-IGF1R mAbs (metformin and figitumumab) have reported to produce synergetic effects in breast cancer cells." (PMID 29455658, 2018). "miR-148a directly targets and down-regulates IGF-1R in breast cancer and over-expression of miR-148a decreased phosphorylated Akt, a component of the PI3K signaling pathway." (PMID 29973528, 2018). "Taken together, we determined that IL-6, CCL2, MMP9, MMP2, and CHOP expression are all inversely correlated with IGF-1R expression in human breast cancer." (PMID 30458886, 2018). "In her2-positive breast cancer and oral squamous cell carcinoma, silencing of miR-375 leads to up-regulation of IGF1R, which was found to be a direct target of miR-375." (PMID 30379973, 2018). "In the present study, we investigated the expression of IGF1R on CTCs of early and metastatic breast cancer patients using immunofluorescence microscopy." (PMID 28766847, 2018). "Our results indicate that IGF1R expression in CTCs is frequently encountered in breast cancer and their incidence decreases in metastatic disease." (PMID 28766847, 2018). "A candidate gene approach has discovered about 70 genes to be associated with preeclampsia and some of the genes overlap with the breast cancer susceptibility genes such as ACE, VEGF, IGF1R and FLT1." (PMID 29361985, 2018). "In E‐cadherin‐positive breast cancer cells, IGF1R resulted in increased cell–cell adhesion and suppressed invasion and metastasis." (PMID 28766847, 2018). "In summary, breast cancer cells exhibits activation of multiple growth promoting factors: IGF-1R, IRS-1, PDZK1 and ER-α." (PMID 29787591, 2018). "The purpose of this study is to identify new IGF-1R inhibitors by using bioinformatics tools for breast cancer treatment." (PMID 29787591, 2018). "The anti-apoptotic and tumorigenic effect of IGF1 is mediated by binding to its cognate receptor, IGF-1R, which is frequently overexpressed in breast cancer." (PMID 30185144, 2018). "IGF1R(+) CTCs are associated with favorable outcomes in early disease stage, suggesting that IGF1R expression is correlated with reduced metastatic potential in breast cancer." (PMID 28766847, 2018).
breast cancer (continued). "Our results suggest that fulvestrant is an effective drug that inhibits the pathogenic/carcinogenic effects of estrogen dependent IGF-1R, IRS-1, ER-α and PDZK1 signaling pathways to control breast cancer progression." (PMID 29787591, 2018). "We demonstrated that mTORC1 inhibition with RAD001 (everolimus) induces IGF-1R/InsR/IRS-1/IRS-2-dependent activation of PI3K/AKT signaling in ER+ breast cancer cells and human tumors treated ex vivo." (PMID 29507656, 2018). "Emerging evidence suggests that IGF-1 and IGF-1R signaling play a pivotal role in the oncogenic transformation, growth and survival of a variety of cancers, including prostate cancer, breast cancer, colon cancer, and myeloma." (PMID 30213025, 2018). "Accordingly, the conditioned media from IGF-1Ea-transfected cells treated with Tun were unable to activate the IGF-1R pathway in human MCF-7 breast cancer cell line." (PMID 29891966, 2018). "To further stratify the expression level of IGF-1R in breast cancers, we queried the METABRIC dataset that includes a larger patient sample size." (PMID 30458886, 2018). "IGF1R has been shown to mediate cancer cell proliferation and survival, and confers resistance to cytotoxic, hormonal, and targeted therapies in breast cancer." (PMID 28766847, 2018). "IGF1 increased motility of metastatic MDA-MB-231BO breast cancer cells through activation of the IGF1R and a dominant negative mutant of IGF1R decreased adhesion, invasion and metastasis of MDA-MB-435 cells." (PMID 30348128, 2018). "In conclusion, IGF1R(+) CTCs are commonly observed in breast cancer and their incidence decreases significantly in metastatic compared to early disease." (PMID 28766847, 2018). "Our observations are in support of IGF1R expression as a favorable prognostic marker in breast cancer." (PMID 28766847, 2018). "IGF1R is overexpressed in breast cancer, cervical cancer, and have a great impact on the pathological process of breast cancer." (PMID 29455664, 2018). "Contradictory results have been reported regarding the prognostic significance of IGF1R in breast cancer." (PMID 28766847, 2018). "In view of the development of IGF1R targeting strategies in breast cancer, we sought to investigate the role of IGF1R expression on CTCs of patients with early and metastatic breast cancer." (PMID 28766847, 2018). "We also evaluated the coexpression of E‐cadherin and IGF1R in a subgroup of CTC‐positive breast cancer patients." (PMID 28766847, 2018). "(2016), 66% of 2.446 postmenopausal patients with hormone receptor‐positive early breast cancer presented high IGF1R expression." (PMID 28766847, 2018). "Of a total of 498 CTCs in metastatic patients [median of 3 CTCs/patient (range, 1–65) CTCs], 339 (68%) expressed IGF1R (Pα = 0.04 and Pβ = 0.002 compared to patients with early breast cancer)." (PMID 28766847, 2018). "In ER-negative tumors we see a tendency towards higher IGF1R expression and in multiple regression analyses adjusting for breast cancer subtype it was confirmed that IGF1R was more expressed in triple negative tumors." (PMID 29486734, 2018). "This was shown to have consequences for metastasis, as IGF1R/CXCR4-expressing breast cancer cells have a higher potential to metastasize to bone." (PMID 29774124, 2018). "Insulin-like growth factor 1 receptor (IGF-1R) is an important therapeutic target for breast cancer treatment." (PMID 29787591, 2018). "METABRIC analysis of several Wnt signaling targets overexpressed in breast cancer revealed that Wnt2 and Frizzled 9 (Fzd9) were inversely correlated with IGF-1R expression in humans." (PMID 30458886, 2018). "In a large cohort of 2.871 patients with early breast cancer, IGF1R expression was correlated with good prognostic indicators and with better survival in the luminal B tumors." (PMID 28766847, 2018). "Previously, it has been observed that IGF-1R and ER-α serve as an important inhibitory targets to control breast cancer pathogenesis." (PMID 29787591, 2018).
breast cancer (continued). "We have also found that fulvestrant is an anti-IGF-1R compound against breast cancer cells and can control tumerogenesis." (PMID 29787591, 2018). "In clinical settings, up-regulation of either IGF1R or HMGA2 protein has been reported to be strongly linked to poor prognosis in malignancies such as gastric cancer and breast cancer." (PMID 29507664, 2018). "In vitro, insulin analogue stimulation increases proliferation of breast cancer cells due to enhanced IGF1R (and INSR) signaling, while exposure to human insulin showed low mitogenic potential." (PMID 29486734, 2018). "In another report, IGF1R immunoreactivity was evident in the majority of breast carcinomas and was correlated with estrogen receptor (ER) expression." (PMID 28766847, 2018). "We conclude that high IGF1R and SphK1 co-expression act together as prognostic indicators and are potentially, dual therapeutic targets for the development of a more effective IGF1R-directed combination breast cancer therapy." (PMID 29207959, 2017). "In a mouse model of breast cancer, local bone resorption was shown to stimulate bone metastasis to that site, while disruption of IGF-1R signaling completely abolished this effect." (PMID 28447314, 2017). "The results provided from this CTS analysis suggest significant breast cancer protection in women with preeclampsia who inherit the protective TT genotype for the IGF1R SNP rs2016347." (PMID 28822014, 2017). "IGF-1 is an important mediator of mammary terminal ductal formation during development, and increased activity of the gland’s IGF-1/IGF1R system has been shown to play a major promoting role in the development of breast cancer." (PMID 28822014, 2017). "Together, our study implicates phenformin-mediated IGF1/IGF1R regulation as a potential anti-cancer mechanism and supports the development of phenformin and other biguanides as breast cancer therapeutics." (PMID 28947975, 2017). "Targeting the type 1 insulin-like growth factor receptor (IGF1R) in breast cancer remains an ongoing clinical challenge." (PMID 29207959, 2017). "The regulation of these pathways is critical in erbB-2-overexpressing breast cancers due to IGF1R and/or erbB-2 crosstalk with ER." (PMID 28193239, 2017). "In a cell study, nuclear InsR-expression was higher in ERα-depleted breast cancer cells and was able to suppress the IGF1R promotor activity in vitro." (PMID 29234306, 2017). "Cancers of the breast, colon, prostate, lungs or Ewing sarcoma belong to malignancies that show high expression of IGF1R." (PMID 28793874, 2017). "Both IGF1 and IGF2 act through the tyrosine kinase insulin-like factor 1 receptor (IGF1R), which is widely overexpressed in multiple childhood sarcomas, including rhabdomyosarcomas, and other cancers such as breast cancer, prostate cancer and lung cancer." (PMID 28793874, 2017). "This is in line with a previous report demonstratinga direct association between InsR overexpression and increasedabundance of hybrid IGF1R/InsR receptors, relative to IGF1R homodimers, in breast cancer specimens." (PMID 28030849, 2017). "Insulin-like growth factors (IGFs) can activate the ER, and crosstalk between insulin-like growth factor 1 receptor (IGF-1R) and ER signaling exists in breast cancer." (PMID 28427228, 2017). "Our studies are the first to report activation of IGF-1R-FoxM1 as a mechanism of invasion in GDF15-overexpressing breast cancers, providing rationale for preclinical evaluation of treatments that co-target IGF-1R and FoxM1." (PMID 29212236, 2017). "High IGF1R activity occurs in up to 50% of breast tumors and is seen across all breast cancer subtypes." (PMID 28446242, 2017). "The type I insulin-like growth factor-1 receptor is a well-described target in breast cancer and multiple clinical trials examining insulin-like growth factor-1 receptor have been completed." (PMID 29152592, 2017). "We have previously demonstrated exposure of MCF-7 breast cancer to an IGF-1R-ATP antagonist inhibitor." (PMID 29152592, 2017).
breast cancer (continued). "We previously reported that FoxM1 is a critical mediator of IGF-1R-stimulated invasion in breast cancer cells." (PMID 29212236, 2017). "In breast cancer, lower expression of IGF-1R was found in tumor specimens than in matched control samples, and positive IGF-1R expression was associated with favorable prognosis." (PMID 28545426, 2017). "In the current study, we demonstrate that GDF15 promotes EMT and invasiveness of breast cancers through insulin-like growth factor-1 receptor (IGF-1R) signaling and transcription factor FoxM1 upregulation." (PMID 29212236, 2017). "GDF15 stable clones and breast cancer cells stimulated with recombinant human GDF15 (rhGDF15) demonstrate activation of insulin-like growth factor-1 receptor (IGF-1R), EMT, and invasion." (PMID 29212236, 2017). "Compared to MMTV‐Her‐2 transgenic mouse mammary tumors, H1047R tumors showed increased upregulation of Wnt/β‐catenin/Axin2, hepatocyte growth factor (Hgf)/Stat3, insulin‐like growth factor 2 (Igf‐2), and Igf‐1R pathways." (PMID 28296140, 2017). "The cytoplasmic and membrane tumor expression of InsR alone and in combination with IGF1R and phospho-IGF1R/InsR in relation to breast cancer outcome has previously been described in the same patient cohort as used in the present study." (PMID 29234306, 2017). "In breast cancer, although both IGFs and insulin have been reported to regulate cell growth, most of the therapeutic agents have targeted IGF-1R function." (PMID 29152592, 2017). "In breast cancer, IGF-1R signaling induces EMT, migration, and invasion in HER2-positive and triple-negative breast cancer." (PMID 29212236, 2017). "There was only one study result (HR = 1.79, 95% CI = 1.08-2.99) describing the OS-breast cancer, indicating significantly detrimental effect for breast cancer treated with IGF-1R inhibitors." (PMID 28427155, 2017). "IGF1R mRNA has been reported as a good prognostic factor specifically in luminal breast cancer subtypes which was also correlated to IGF1R protein expression." (PMID 29207959, 2017). "Currently, more than ten IGF/IGF-1R inhibitors are under clinical investigation for various cancers, including breast cancer." (PMID 28989976, 2017). "HS578T human breast cancer cell lines overexpressing the H1047R showed threefold, and E545K mutants showed fivefold higher IGF‐1R levels than the parental HS578T cells." (PMID 28296140, 2017). "Knockdown IGF-1R delays tumor growth and induces proinflammatory cytokines in a mouse breast cancer model." (PMID 28674429, 2017). "In breast cancer lines, resistance to AKT inhibition is associated with increased expression of RTKs HER3, IR and IGF1R." (PMID 28640835, 2017). "In order to further understand the prognostic and therapeutic implications of IGF1R and SphK1 co-expression in breast cancer we have analyzed their distribution in human breast cancer formalin-fixed paraffin embedded (FFPE) tissue samples." (PMID 29207959, 2017). "The prognostic (overall survival, OS) and therapeutic (anti-endocrine therapy) co-contribution of IGF1R and SphK1 were investigated using breast cancer patient samples (n = 236) for immunohistochemistry to measure total and phosphorylated IGF1R and SphK1." (PMID 29207959, 2017). "In agreement with its tumor suppressor role, exogenous BRCA1 expression in breast cancer cells led to reductions in endogenous IGF1R protein and mRNA levels and a marked decrease in IGF1R promoter activity." (PMID 28706506, 2017). "In initial experiments, we measured endogenous BRCA1 and IGF1R levels in a number of breast cancer cell lines expressing a wild-type or a mutant BRCA1 gene." (PMID 28706506, 2017).